ABCA1 (ATP binding cassette subfamily A member 1)
Diseases named in the same sentence as ABCA1 in open-access papers (continued):
Sharing a sentence is not in itself a finding about the gene and the disease.
atherosclerosis (continued). "Forced expression of AI662270 promoted foam cell formation by acting as an Abca1 inhibitor and repressing the SR-BI expression, accelerating the progression of atherosclerosis." (PMID 36755320, 2023). "Our study showed that, among the target genes of LXRα, key lipid processing genes including Abcg1, Lpl, Pltp, and Abca1 have a strong positive correlation with atherosclerosis." (PMID 37301941, 2023). "LXRα, an important regulator of cholesterol efflux in atherosclerosis, has been shown to be down‐regulated in oxLDL‐treated macrophages, as its downstream membrane proteins ABCA1 and ABCG1 were concomitantly decreased." (PMID 37905351, 2023). "More importantly, gaining a deeper understanding of the mechanism by which MP promotes the functionality of ABCA1 holds the potential to provide insights into strategies for the prevention and amelioration of atherosclerosis." (PMID 38139111, 2023). "The role of Abca1, Abcg1, and Pltp in foam cells is particularly apparent in the late stage of atherosclerosis." (PMID 36910156, 2023). "These genes are involved in cholesterol metabolism (Abca1, Abcg8, Abcg5, Lpl, Cyp7a1, and Pltp), lipid and atherosclerosis (Abca1, Il1b, Ccl2, and Abcg1), bile secretion (Abcg8, Abcg5, and Cyp7a1), and IL-17 signaling pathway (Ccl7, Il1b, and Ccl2)." (PMID 37301941, 2023). "For instance, a new circRNA circDENND1B characterized by circRNA sequencing was discovered to control the interface between inflammation and cholesterol transport through miR-17-5p/Abca1 axis in atherosclerosis." (PMID 35786385, 2022). "Animal experiment has confirmed that an imprinted antisense IncRNA in the KCNQ1 gene promotes macrophage lipid accumulation and accelerates the development of atherosclerosis through the miR-452-3p/HDAC3/ABCA1 pathway." (PMID 36539828, 2022). "In pigs, ABCA1 overexpression is directly associated with an increase in HDL levels and polymorphisms on this gene have been associated with atherosclerosis risk score." (PMID 34991486, 2022). "In apoE-/- mice, quercetin and semen celosiae have been found to promote ABCA1 expression to protect against atherosclerosis." (PMID 35743794, 2022). "These and other data suggest that ABCA1 is a promising target for drug action to prevent and treat atherosclerosis." (PMID 36363640, 2022). "kcnq1ot1 promotes macrophage lipid accumulation and accelerates the development of atherosclerosis via the miR-452-3p/HDAC3/ABCA1 pathway." (PMID 35806493, 2022). "ApoA-IV prevents thrombosis by inhibiting platelet aggregation and hyperactivity, enhances cholesterol efflux by ABCA1, activates LCAT, prevents the oxidation of LDL molecules, and attenuates the risk for the development of atherosclerosis." (PMID 36297390, 2022). "(2021) has reported that the knockdown of miR‐200b‐3p alleviated lipid accumulation and promoted cholesterol efflux, which were two characteristics in the pathogenesis of atherosclerosis, by targeting ABCA1." (PMID 35261213, 2022). "In vitro, Mφs stimulated with IL-13 increased the uptake of oxLDL by CD36 upregulation and induced the expression of the lipid exporter (ABCA1), preventing foam cell formation, which is a major driver of atherosclerosis." (PMID 35488301, 2022). "It has been shown that ABCA1 expression in macrophages can protect against atherosclerosis through reduction in cholesterol in macrophage plasma membrane and lipid raft content, which suppresses proinflammatory MyD88-dependent signaling pathways." (PMID 36363591, 2022). "Hypoxia plays a key mechanistical role during atherosclerosis and upregulates ABCA1 in macrophages through HIF1α transcription factor." (PMID 36407436, 2022). "In vascular smooth muscle cells, the inhibition of myocardin regulates ABCA1 to prevent atherosclerosis." (PMID 35743794, 2022).
atherosclerosis (continued). "MiR-93 is reported to inhibit ABCA1 expression, hence it leads to impaired macrophage cholesterol efflux, promoting atherosclerosis progression." (PMID 36361845, 2022). "lincRNA PCA3 inhibits lipid accumulation and atherosclerosis by promoting ABCA1-mediated cholesterol efflux for by sponging miR-140-5p and enhancing RFX7." (PMID 36011386, 2022). "Paeonol, a phenolic compound found in Paeonia suffruticosa, retarded atherosclerosis progression in apoE−/− mice by upregulation of ABCA1-mediated enhancement of cholesterol efflux and downregulation of CD36." (PMID 36297390, 2022). "Yin-xing-tong-mai and Sini decoctions increase ABCA1 expression in macrophages by activating the PPARγ–LXRα pathway to attenuate atherosclerosis." (PMID 35743794, 2022). "Together, the changes in expression of ABCA1 in patients with atherosclerosis and atherosclerotic diseases have been well confirmed experimentally." (PMID 34940525, 2021). "In other studies, the level of ABCA1 mRNA was also decreased in macrophages of patients with atherosclerosis, and the content of ABCA1 was decreased." (PMID 34940525, 2021). "At the same time, these authors showed that the level of ABCA1 mRNA is reduced in the leukocytes of patients with atherosclerosis." (PMID 34940525, 2021). "Studies of the overexpression and knockout of ABCA1 in mice cells provide insight into its role in the pathogenesis of atherosclerosis." (PMID 34940525, 2021). "Experiments in ApoE −/− mice have shown that the increased methylation of the promoter region of ABCA1 decreases its expression and promotes atherosclerosis development." (PMID 34940525, 2021). "Studies in miR-33−/− mice, including double ApoE−/− knockout, have shown that miR-33 deficiency serves to raise HDL-C, increase cholesterol efflux from macrophages via ABCA1, and prevent the progression of atherosclerosis." (PMID 34940525, 2021). "We have previously reported that ApoAI, PON1, and ABCA1 levels in the small intestine are inversely correlated with the severity of atherosclerosis." (PMID 34944413, 2021). "In general, deficiency or downregulation of ABCA1 expression leads to a significant decrease in serum HDL levels and an increased risk of atherosclerosis." (PMID 33802600, 2021). "It was also shown to protect against high-fat induced atherosclerosis by upregulating ABCA1 in ApoE−/− mice." (PMID 34360839, 2021). "Together, circRNA circDENND1B and the considered above lncRNA MALAT1, CHROME, GAS5, MEG3 function as ceRNAs and bind miRNAs that suppress the expression of ABCA1, which increases the level of ABCA1 mRNA and prevents the development of atherosclerosis." (PMID 34940525, 2021). "Data have shown that ablating endothelial ABCA1 expression exacerbates atherosclerosis in mice, while overexpressing ABCA1 in endothelial cells is atheroprotective in mice." (PMID 34564456, 2021). "We and others previously reported that administration of leonurine, kuwanon G or dihydromyricetin inhibits lipid accumulation in THP-1 macrophages and protects against atherosclerosis in mice by activating the LXRα-ABCA1/ABCG1 signaling pathways." (PMID 33692340, 2021). "IFN-β fuels the formation of macrophage foam cells via a macrophage scavenger receptor class A (SR-A)-mediated cholesterol influx and an ATP-binding cassette transporter (ABCA1)-mediated efflux of mechanisms, thus expediting the incidence of atherosclerosis." (PMID 34512320, 2021).
atherosclerosis (continued). "As circDENND1B harbors eight binding sites for miR-17-5p, and miR-17-5p has been reported to modulate the progress of atherosclerosis via Abca1, we investigated the relationship between circDENND1B and miR-17-5p." (PMID 33996813, 2021). "Overall, the current investigation demonstrates that PBMT, a non‐invasive treatment, can ameliorate WD‐induced atherosclerosis through promoting the ABCA1‐medicated cholesterol efflux to inhibit foam cells formation." (PMID 33951300, 2021). "Mutations in ABCA1 caused Tangier disease and exhibited a reduced cholesterol efflux, low HDL‐C level and an increased risk to develop atherosclerosis." (PMID 33951300, 2021). "Due to its role in the reverse transport of cholesterol, ABCA1 is considered an important participant in the pathogenesis of atherosclerosis." (PMID 34564491, 2021). "Down-regulation of ABCA1 leads to accumulation of intracellular lipids, promoting FC generation during atherosclerosis." (PMID 33483751, 2021). "Lastly, profiling microRNA in BMDM–HG-exo and plasma EVs from diabetic subjects with advanced atherosclerosis converged on miR-486-5p as commonly enriched and recognized in dysregulated hematopoiesis and Abca1 control." (PMID 34381972, 2021). "The increased methylation of the ABCA1 promoter was also found in patients with early atherosclerosis." (PMID 34940525, 2021). "LXR and RXR agonists are attractive candidates for atherosclerosis therapy, since they are capable of inducing ABCA1 expression." (PMID 34564456, 2021). "ATP-binding cassette (ABC) transporter A1 (ABCA1) and miR-33-5p play crucial roles in atherosclerosis by controlling cholesterol efflux." (PMID 34517822, 2021). "Due to the anti-inflammatory properties of ABCA1, it can effectively maintain the cholesterol homeostasis in mouse macrophages and inhibit the inflammatory response of atherosclerosis." (PMID 33767629, 2021). "As can be seen from most genome studies presented, mutations in ABCA1 cause the loss of its function to promote the reduction of cholesterol efflux, HDL levels, and increase the risk of atherosclerosis and CVD." (PMID 34940525, 2021). "As the methylation of the promoter region of ABCA1 contributes to atherosclerosis development, substances that inhibit methylation can prevent the downregulation of this gene and promote cholesterol efflux." (PMID 34940525, 2021). "Endothelial ABCA1 expression protects against atherosclerosis and this atheroprotective effect is partially attributed to enhancing apoAI-mediated cholesterol efflux." (PMID 34564456, 2021). "Several ncRNAs have been described that are involved in the downregulation of mRNA ABCA1 and in the progression of atherosclerosis, including lnc-HC." (PMID 34940525, 2021). "A decrease in ABCA1-mediated reverse cholesterol efflux and impaired efferocytosis mediated by enhanced CD 47 expression over calreticulin can lead to progression of atherosclerosis lesions." (PMID 34944106, 2021). "LRP1 can also protect against atherosclerosis by regulating the expression of ATP-binding cassette transporter A1 (ABCA1)." (PMID 34124208, 2021). "This review summarizes the progress in studying the genomic variants of ABCA1, ABCG1, and SCARB1, and the regulation of their function at transcriptional and post-transcriptional levels in atherosclerosis." (PMID 34940525, 2021). "Taken together, these findings suggest that kcnq1ot1 promotes macrophage lipid accumulation and accelerates the development of atherosclerosis through the miR-452-3p/HDAC3/ABCA1 pathway." (PMID 33293505, 2020). "In this article, we review the roles of ANXA1 in atherosclerosis and focus on the crosstalk of ABCA1 and ANXA1." (PMID 32894039, 2020).
atherosclerosis (continued). "Given the complexity of lncRNA action mechanisms, it is possible that kcnq1ot1 regulates ABCA1 expression and affect atherosclerosis progression by other pathways." (PMID 33293505, 2020). "According to the TargetScan7.2 database, mir-17a-5p and mir-18a are associated with ATP-binding cassette transporter A1 (ABCA1) and ATP-binding cassette transporter G1 (ABCG1), which are the important factors in atherosclerosis." (PMID 32908568, 2020). "ABCA1 is the key to macrophage cholesterol efflux and has a protective influence on atherosclerosis." (PMID 32002588, 2020). "Mutations in ABCA1 gene cause Tangier disease, which is characterized by extremely low plasma HDL-C levels and premature atherosclerosis." (PMID 33959213, 2020). "Alteration of cholesterol metabolism, at least in terms of ABCA1 regulation, and circulating cholesterol levels cannot explain increased atherosclerosis in our animals." (PMID 32273567, 2020). "Further, CE and FC accumulation leads to the inhibition of LAL and ABCA1 activity, which is believed to contribute to the pathogenesis of atherosclerosis." (PMID 32664594, 2020). "Quercetin demonstrated a protective effect against atherosclerosis partly through increasing the expression of ABCA1." (PMID 32435189, 2020). "It is now well established that ABCA1 plays a critical role in the prevention of macrophage foam cell formation and atherosclerosis by mediating the active transport of intracellular cholesterol and phospholipids to apoA-I, the major lipoprotein in HDL." (PMID 32375652, 2020). "In general, APOE lipidation is highly reliant on the ATP-binding cassette transporter A1, or ABCA1, which moves lipids into apolipoproteins and is known to protect against atherosclerosis." (PMID 32005122, 2020). "This has led the research focus to shift towards looking at the anti-inflammatory benefits of ABCA1 in atherosclerosis." (PMID 32977800, 2020). "ABCA1/G1 is known to mediate efflux of cellular cholesterol and phospholipids, which is the target for therapy of anti-atherosclerosis." (PMID 32408171, 2020). "In summary, the present study has demonstrated an important role of kcnq1ot1 in facilitating atherosclerosis development and revealed a novel mechanism for ABCA1 regulation." (PMID 33293505, 2020). "The molecular defect in the ABCA1 gene results in Tangier disease, which is characterized by HDL deficiency, proteinuria, and premature atherosclerosis." (PMID 33426085, 2020). "Baicalin potentially exerts anti-atherosclerosis effects through the PPARγ–LXRα–ABCA1/ABCG1 pathway by promoting cholesterol efflux from macrophages and delaying the formation of foam cells." (PMID 33321972, 2020). "It was shown that Qu can induce the expression of ABCA1 in THP-1 derived foam cells, enhance the apoA-I-dependent cholesterol efflux, and reduce the risk of atherosclerosis." (PMID 32565865, 2020). "In this study, we assessed the effects of Cav on ABCA1 expression and cholesterol efflux that are relevant to the process of atherosclerosis." (PMID 31635197, 2019). "Blocking HMGB1 release by EP or inhibiting TLR4 activation by TAK-242 almost reversed CUMS-induced the drownregulation of PPARγ-LXRα-ABCA1 and impeded the development of atherosclerosis in apoE-/- mice." (PMID 30881312, 2019). "MicroRNA-33 (miR-33) is an intronic miRNA that encodes sterol-regulatory element-binding factor-2, which is involved in atherosclerosis, as it is the target of ATP-binding cassette transporter A1 (ABCA1) and ATP-binding cassette transporter G1 (ABCG1)." (PMID 30761836, 2019). "Proteasomal degradation regulated macrophage ABCA1 levels and inhibition of ABCA1 protein degradation increases the cholesterol efflux capacity of an intimal macrophage, which potentially slows down atherosclerosis progression." (PMID 31195722, 2019).
atherosclerosis (continued). "In the same study, apabetalone, a small molecule BET-inhibitor, used in experimental therapeutics of atherosclerosis and known to induce production of ApoA-I, reduced the ABCA1-driven proliferative and invasive behavior of CA cells." (PMID 31374929, 2019). "Due to the critical role of macrophage regarding ABCA1 expression and cholesterol efflux capacity in the pathogenesis of atherosclerosis, we used THP-1 macrophages as our further in vitro model." (PMID 31635197, 2019). "The relationship between apoptosis-triggered CSN6 cleavage and ABCA1 stability, thus, needs to be studied further in atherosclerosis-relevant models." (PMID 31195722, 2019). "The expression of positive regulators of atherosclerosis (ABCA1, ABCG1) was higher in the P group than that in the RP group (P < 0.05), and the opposite effect was observed for negative regulators (ACAT1, CD36)." (PMID 30105261, 2018). "TTC39B deficiency displayed increased HDL-cholesterol levels associated with increased enterocyte Abca1 expression, increased LXR protein, decreased fatty liver, decreased LDL levels, and reduced atherosclerosis." (PMID 29593532, 2018). "MicroRNA 33 (miR-33) targets ATP-binding cassette transporter A1 (ABCA1), and its deficiency increases serum high-density lipoprotein (HDL)-cholesterol (HDL-C) and ameliorates atherosclerosis." (PMID 29712758, 2018). "The Tall group has extensively described the protective role of the LXR target genes Abca1, Abcg1, and Apoe in hematopoietic cell types, and their contributions to atherosclerosis." (PMID 30087224, 2018). "The ABCA1 overexpression accelerated atherosclerosis by a delayed catabolism of apoB-containing lipoproteins (VLDL and LDL)." (PMID 30037080, 2018). "The importance of macrophage ABCA1 expression in atherosclerosis has been further demonstrated in bone marrow transplantation of ABCA1 null macrophages in hyperlipidemic mice." (PMID 30271349, 2018). "In contrast, C57Bl mice overexpressing hepatic ABCA1 and fed a cocoa butter diet with 1.25% cholesterol and 0.5% cholic acid for 15 weeks displayed decreased atherosclerosis compared with control mice." (PMID 30037080, 2018). "In contrast, ENA-78 reveals a protective role in atherosclerosis by increasing expression of the cholesterol efflux regulatory protein ABCA1 and enhancing cholesterol efflux activity in macrophages." (PMID 30596089, 2018). "Macrophages export excessive cholesterol (cholesterol efflux) through ATP-binding cassette transporter A1 (ABCA1) to counter the progression of atherosclerosis." (PMID 29970865, 2018). "This novel synthetic chalcone derivative that targets ABCA1 critical in foam cell formation can be beneficial to the prevention of atherosclerosis." (PMID 29970865, 2018). "It has also been reported that ABCA1 and ABCG1 deficiency in macrophages increases inflammation and accelerates atherosclerosis in mice." (PMID 29137283, 2017). "The miR-144-3p target ABCA1 is involved in the progression of atherosclerosis via the promotion of proinflammatory cytokine production in apolipoprotein E KO (apoE-/-) mice." (PMID 29050208, 2017). "The effect of overexpressing proteins involved in HDL biogenesis, especially apoA-1 and ABCA1, on the development of atherosclerosis has been the subject of several investigations." (PMID 28278274, 2017). "Studies have established the role of ABCA1 in the prevention of atherosclerosis in mediating lipid efflux to apolipoproteinA-1 (apoA-1), the major lipoprotein in high density lipoprotein (HDL) transport." (PMID 29113088, 2017).